INS (insulin)
Diseases named in the same sentence as INS in open-access papers (continued):
Sharing a sentence is not in itself a finding about the gene and the disease.
diabetic retinopathy (continued). "Patients with massive proteinuria were more likely to receive insulin and have advanced diabetic retinopathy." (PMID 35213636, 2022). "BBR can improve diabetic retinopathy in type I and II diabetic animals receiving insulin therapy, reducing neovasculature and neural cell damage in the eyes and therefore supplemented the therapeutic outcome of insulin therapy." (PMID 34803500, 2021). "Preliminary evidence supports associations between miR-20b and risk for T2DM, including insulin uptake in skeletal muscle and T2DM-related complications including diabetic retinopathy and endothelial cell function." (PMID 34425916, 2021). "This vascular and molecular phenotype has clear parallels with diabetic retinopathy and future studies should explore the role of diminished pericyte insulin signaling in this disease." (PMID 34460911, 2021). "The application of modern insulin pumps with continuous glucose monitoring systems has greatly diminished the incidence rate of early symptoms of diabetic retinopathy in the pediatric population." (PMID 34205677, 2021). "Jones in the Norfolk Diabetic Retinopathy Study showed that compared to diet control only, the adjusted hazard ratio (95% CI) = 2.17 (1.68–2.81) if participants were using insulin." (PMID 34912295, 2021). "Our finding also suggests that berberine can effectively control the progression of diabetic retinopathy in insulin-treated diabetic mice." (PMID 34803500, 2021). "This phenotype mimics elements of diabetic retinopathy, and future work should evaluate pericyte insulin signaling in this disease." (PMID 34460911, 2021). "In order to prevent the development of chronic diabetes complications, including diabetic retinopathy, some patients need to use insulin to optimize blood glucose control." (PMID 34955862, 2021). "Taken together, in this study we reported the novel function of BBR in improving insulin therapy-induced diabetic retinopathy in both type I and II DM animals." (PMID 34803500, 2021). "Within our Navajo American Indian study population, the prevalence of diabetic retinopathy was 13.3%, which is lower than the 29% that has been previously reported within the Navajo of Northeast Arizona that was insulin-dependent." (PMID 33171720, 2020). "Insulin-loaded chitosan nanoparticle/ICNPH (1:20 ratio) reduced retinal cell apoptosis greater compared to insulin alone in an in vivo assay using diabetic retinopathy model rats through a single subconjunctival injection." (PMID 33171799, 2020). "In this study, we compared the effect on diabetic retinopathy (DR) between oral antidiabetic drugs (OADs) alone and in combination with basal insulin‐supported OADs therapy (BOT)." (PMID 30973204, 2019). "In a recent study, we reported and discussed the worsening of diabetic retinopathy observed after rapid lowering of blood glucose with insulin." (PMID 29017477, 2017). "The predictors identified in these three studies, such as age, creatinine, blood pressure, albuminuria, diabetic retinopathy, and insulin use, were similar to those in our model." (PMID 28860599, 2017). "Further evidence drawn from more recent systematic review and meta-analysis support previous findings and highlight the early worsening effect of insulin on the progression of diabetic retinopathy." (PMID 29017477, 2017). "The subgroup of LADA patients with diabetic retinopathy (DR) who were treated with insulin had a lower ADDQoL average weighted impact score than the other diabetic groups." (PMID 29062603, 2017). "Many epidemiological studies supported the fact that insulin therapy is a key factor in the occurrence of early worsening of diabetic retinopathy." (PMID 29017477, 2017). "Patients with diabetic retinopathy were more likely to be female, have longer disease duration, and be hypertensive and prescribed insulin." (PMID 26382215, 2015). "Patients with diabetic retinopathy had higher disease duration, insulin dose, HbA1, microalbuminuria and adiponectin." (PMID 27275296, 2015).
diabetic retinopathy (continued). "Patients with diabetic retinopathy had a significant higher insulin dose, disease duration, HbA1, urinary albumin/creatinine ratio and serum adiponectin." (PMID 27275296, 2015). "When diabetic retinopathy rats were treated with CrHis, significant increases in blood glucose, HbA1c, insulin and total cholesterol levels were observed in diabetic retinopathy rats." (PMID 25652875, 2015). "Both insulin and IGF-1 have been implicated in the control of retinal endothelial cell growth, neovascularization and diabetic retinopathy." (PMID 26075045, 2015). "Complications of diabetic retinopathy were also shown to slow significantly while the same trend was observed for the carbohydrate metabolic profile as reflected in improved values of insulin expression and glucose transporter proteins." (PMID 25652875, 2015). "Treatment of diabetic retinopathy rats with CrHis succeeded to normalize the lower retina insulin level." (PMID 25652875, 2015). "Only 3 studies in the STZ and non-insulin-dependent diabetic rat models have evaluated the consequences of diabetic retinopathy on light-induced FOS protein in the SCN." (PMID 25006976, 2014). "Hypomagnesaemia has been incriminated in the development and progression of diabetic retinopathy and defective release of insulin." (PMID 25598753, 2014). "one hundred (n=100) elderly outpatients with diabetic retinopathy takingantihypertensives and/or oral antidiabetics/insulin were interviewed." (PMID 25591084, 2014). "L-carnitine, which facilitates the transport of long chain fatty acids into mitochondria, improves insulin sensitivity in insulin-resistant patients, suggesting a possible beneficial effect on the progression of diabetic retinopathy." (PMID 24905410, 2014). "Due to APN’s association with enhanced insulin sensitivity, APN deficiency is believed to be closely related with the pathological progression of diabetic retinopathy." (PMID 23922494, 2013). "The Wisconsin Epidemiological Study of Diabetic Retinopathy recruited a community-based cohort with a high prevalence of younger, insulin-requiring patients, and the incidence and progression of retinopathy was determined with fundus photography." (PMID 23316296, 2012). "More recent studies show other potential mechanisms by which insulin affects DR, including the regulation of α- and γ-crystallins, factors potentially involved in the inflammatory process in diabetic retinopathy." (PMID 21293735, 2011). "Penn State University holds intellectual property related to the use of periocular insulin to treat diabetic retinopathy." (PMID 22046295, 2011). "Insulin has been chosen as a model protein, but it has also been recently proposed for its potential use in the local treatment of diabetic retinopathy." (PMID 19190734, 2009). "Tailored insulin therapies could represent innovative strategies for managing or slowing the progression of diabetic retinopathy." (PMID 40510890, 2025). "One putative mechanistic explanation for the increased rates of diabetic retinopathy in our study may be that insulin pump commencement resulted in a more rapid improvement in glycaemic control." (PMID 40390300, 2025). "The translational potential of modulating RPE insulin production could open innovative strategies for the prevention or treatment of diabetic retinopathy and other retinal degenerative disorders." (PMID 41301488, 2025). "Omeprazole-induced AhR activation can help prevent diabetic retinopathy; however, long-term exposure may lead to metabolic alterations, including increased insulin and blood glucose levels." (PMID 41440753, 2025). "In contrast, a study conducted in Saudi Arabia to investigate the incidence of diabetic retinopathy between insulin-dependent and non-insulin-dependent patients found that insulin usage was associated with retinopathy events (OR 1.36; 95 % CI 1.07–1.73)." (PMID 39295783, 2024).
diabetic retinopathy (continued). "TZP was associated with a lower risk of “diabetic retinopathy” vs. GLP-1RA as a class, which persisted vs. lixisenatide, liraglutide, semaglutide and dulaglutide, and following restriction of the analysis to exclude patients on concomitant insulin treatment." (PMID 39141075, 2024). "Therefore, if the beneficial effects of protamine on DR are shown, we can easily prevent or delay diabetic retinopathy by prescribing protaminated insulins instead of insulin alone." (PMID 37828117, 2023). "Thus, this study aimed to compare the effect of protamineated insulin (PIns) with insulin on diabetic retinopathy." (PMID 37828117, 2023). "Insulin is proved to have angiogenic ability thereby may worsen the diabetic retinopathy (DR) progression." (PMID 37828117, 2023). "An intensive insulin therapy slowed progression of diabetic retinopathy by 54%." (PMID 37423944, 2023). "In addition, the chance of diabetic retinopathy in protaminated insulin group is less than insulin group." (PMID 37828117, 2023). "Overall, it seems that insulin and apelin have angiogenic effects and this may be one of the mechanisms of diabetic retinopathy in diabetic patients." (PMID 37828117, 2023). "High-dose insulin might be one of the reasons for the transient worsening of diabetic retinopathy during intensive insulin treatment." (PMID 35459162, 2022). "This insulin-dependent T2D stage is refractory to treatment, with a need for exogenous insulin coupled to insulin resistance, leading to high rates of secondary pathologies, such as diabetic foot or diabetic retinopathy." (PMID 36291702, 2022). "The pharmacodynamics of various insulin products show different effects on diabetic retinopathy." (PMID 35459162, 2022). "However, some studies have indicated that intensive insulin therapy can aggravate diabetic retinopathy at an early stage." (PMID 35459162, 2022). "He had diabetic retinopathy and was being treated with insulin." (PMID 34920746, 2021). "He had diabetic retinopathy and had been treated with insulin for 3 years." (PMID 34920746, 2021). "Probably the worsening of diabetic retinopathy attributed to insulin use might result from ROS signaling via activation VEGF expression." (PMID 29017477, 2017). "This explains the role of insulin, the different clinical features found on retinal examination, why diabetic retinopathy is more pronounced in individuals with pre-existing retinal lesions (worsening) and rare in individuals without any pre-existing retinal abnormality." (PMID 29017477, 2017). "The patients with a degree of diabetic retinopathy greater than mild (moderate/severe/proliferative) presented with higher glycated hemoglobin, systolic blood pressure, triglycerides, and urinary albumin excretion and were more likely on insulin treatment." (PMID 27200379, 2016). "Additionally, we wanted to test the effects of salicylate therapy on insulin signaling cascades on 2 key retinal cell types involved in diabetic retinopathy, the Müller cell and retinal endothelial cell." (PMID 25874611, 2015). "Moreover, with the progression of diabetic retinopathy, patients turned to have higher prevalence of primary hypertension, higher prevalence of peripheral vascular sclerosis, higher proportion with insulin treatment." (PMID 24614131, 2014). "The use of insulin did not influence gene expression patterns; however, increased serum glucose level was associated with the induction of genes related to diabetic retinopathy." (PMID 24885568, 2014). "Our previous studies in retinas of diabetic rats have shown that Compound 49b, a novel β-adrenergic receptor agonist, prevented diabetic changes by increasing IGFBP-3 and decreasing TNFα, thus restoring insulin signaling and protection against diabetic retinopathy." (PMID 24695399, 2014). "An insulin pump may delay the development of diabetic retinopathy and decrease the need for an intervention in the eye." (PMID 24688225, 2014).
diabetic retinopathy (continued). "The use of insulin was accompanied by a retinal picture similar to that of the control group, while the combined use of sorafenib and insulin prevented the development of both morphological signs of diabetic retinopathy (DR) and an increase in the intensity of VEGF-positive staining." (PMID 41169477, 2025). "However, unmeasured confounding may have influenced the result for the diabetic retinopathy outcome in the SGLT2i + insulin vs control analysis given the low E-value." (PMID 38584180, 2024). "Therefore, we speculated that enhancing autophagy activity was one of the potential mechanisms of insulin therapy for diabetic retinopathy." (PMID 34955862, 2021). "We postulate that exogenous insulin could act synergistically with the vascular endothelial growth factor expressed by ischemic retina so as to trigger vascular proliferation and the worsening of diabetes retinopathy." (PMID 29017477, 2017). "Our analysis identified only 12 “diabetic retinopathy” events; TZP was associated with an increased risk of “diabetic retinopathy” compared to all other drug but with a consistently lower risk vs. GLP-1RA and insulin use, which could represent a proxy for more advanced stages of disease." (PMID 39141075, 2024). "However, previous research has hypothesized that exogenous insulin acts synergistically with vascular endothelial growth factor expressed by the ischemic retina, thereby triggering vascular proliferation and worsening of diabetes retinopathy." (PMID 34337073, 2021). "In diabetic retinopathy, there is a decrease in GFAP immunoreactivity in astrocytes, and this is restored when insulin is administered, so insulin may regulate various aspects of retinal glial cell metabolism." (PMID 35625676, 2022). "During the follow-up period of 6 months after insulin intensification, the fundoscopy findings of all patients were stable, without diabetic retinopathy progression." (PMID 35459162, 2022). "Moreover, there were marked differences in insulin usage, 24-h Upro, UACR, eGFR, and diabetic retinopathy rate between the microalbuminuria and macroalbuminuria groups." (PMID 36237191, 2022). "The patients with diabetic retinopathy more frequently received insulin treatment compared with those without." (PMID 33239667, 2020). "Lispro insulin improves the glycemic control during pregnancy with no adverse impact on the progression of diabetic retinopathy." (PMID 30786308, 2019). "Likewise, rats with diabetic retinopathy who were supplemented with chromium for 12 weeks showed improvement in the gene expression of GLUT-1, GLUT-3, and insulin." (PMID 30546347, 2018). "Our theory is based on the fact that high dose of exogenous insulin could act synergistically with VEGF expressed by ischemic retina so as to trigger vascular proliferation and worsening of diabetic retinopathy." (PMID 29017477, 2017). "Compared to other models of rodent diabetic retinopathy, our model has the advantage of being short, having a pronounced phenotype, and not requiring insulin treatment for animal survival." (PMID 24278148, 2013). "Notably, as current therapies for Diabetic Retinopathy (DR) primarily target advanced stages, none of these individuals received additional treatment beyond regular insulin therapy." (PMID 38700545, 2024). "Therefore, the interacted miRNAs may cause progression of T2D pathogenies regulating MAPK signaling, insulin signaling, TGF-β signaling, mTOR signaling pathways, and diabetic retinopathy signaling pathways." (PMID 38096208, 2023). "This may explain the occurrence of diabetic retinopathy with new vessels in presence of insulin and not with oral antidiabetic agents." (PMID 29017477, 2017). "Gene expression changes not rescued or prevented by insulin treatment may be critical to the pathogenesis of diabetic retinopathy, as it occurs in diabetic patients receiving insulin replacement, and are prototypical of metabolic memory." (PMID 21575160, 2011).
diabetic retinopathy (continued). "Additionally, they had higher incidence of insulin therapy than the controls (diabetics without diabetic retinopathy)." (PMID 18682813, 2008). "However, plenty of clinical evidence has shown that insulin treatment has no beneficial effect on diabetic retinopathy, one of the major complications in diabetic patients; instead, it may even increase the risk of incidence of this disease." (PMID 34803500, 2021). "For instance, the 10-year incidence of diabetic retinopathy in patients with T1DM is nearly 36%, while the 20-year incidence for T2DM is 84% in those taking insulin and 53% in those not taking insulin." (PMID 33434220, 2021).